METTL3 (methyltransferase 3, N6-adenosine-methyltransferase complex catalytic subunit)
Diseases named in the same sentence as METTL3 in open-access papers (continued):
Sharing a sentence is not in itself a finding about the gene and the disease.
esophageal squamous cell carcinoma (28 papers, 2020 to 2026). Esophageal squamous cell carcinoma (ESCC) is a type of esophageal carcinoma (EC) that can affect any part of the esophagus, but is usually located in the upper or middle third. "METTL3 is highly expressed in esophageal squamous cell carcinoma (ESCC) and is linked to poor prognosis in patients." (PMID 40271153, 2025). "They demonstrated that METTL3-mediated m6A formation in RNA causes DNA demethylation in adjacent genomic loci in both normal and esophageal squamous cell carcinoma (ESCC) cells." (PMID 39199304, 2024). "Wang W found that METTL3 expression was significantly elevated in esophageal squamous cell carcinoma and was associated with poor patient prognosis." (PMID 36386128, 2022). "Moreover, high expression of METTL3 was significantly associated with poor OS in esophageal squamous cell carcinoma (HR = 2.20; 95% CI: 1.59–3.05, p < 0.001; I2 = 0.0%, p = 0.436) and oral squamous cell carcinoma (HR = 2.16; 95% CI: 1.33–3.49, p = 0.002; I2 = 0.0%, p = 0.602)." (PMID 36347025, 2022). "METTL3 upregulates the m6A modification of adenomatous polyposis coli (APC) RNA in esophageal squamous cell carcinoma (ESCC) cells, which recruits YTHDF for APC mRNA degradation." (PMID 37192910, 2023). "METTL3 can promote the cell proliferation of esophageal squamous cell carcinoma (ESCC) by decreasing APC expression mediated by APC mRNA m6A‐dependent YTHDFs binding." (PMID 36260366, 2023). "For example, METTL3 promotes the development of esophageal squamous cell carcinoma (ESCC) through the stabilization of NOTCH1 and EGR1 mRNA, followed by activation of Notch and EGR1/Snail signaling pathways." (PMID 37965577, 2023). "The expression of METTL3 mRNA in esophageal squamous cell carcinoma and esophageal adenocarcinoma was significantly different (p = 0.044)." (PMID 32626532, 2020). "Meanwhile, the long non-coding RNA AP001885.4 promotes the expression of c-myc by inducing histone lactylation and NF-κB (p65)-dependent transcriptional activation, enhancing its mRNA stability through METTL3, and ultimately facilitating the proliferation of esophageal squamous cell carcinoma." (PMID 41458606, 2025). "However, in our study, with EC109 esophageal squamous cell carcinoma cells, we found significant differences in the binding partners of METTL3 and METTL14." (PMID 38965238, 2024). "In our study, we discovered that the expression of methyltransferase-like 3 (METTL3) was significantly elevated in human esophageal squamous cell carcinoma (ESCC) tissues." (PMID 41262526, 2026). "In this study, we analysed TCGA data and separated 200 paired oesophageal squamous cell carcinoma (ESCC) specimens and their adjacent normal tissues and demonstrated that methyltransferase-like 3 (METTL3) is highly expressed in tumour tissues." (PMID 34155197, 2021). "However, the roles of METTL3 in esophageal squamous cell carcinoma (ESCC) are still unclear." (PMID 34094960, 2021). "In esophageal squamous cell carcinoma, YTHDF1 is involved in m6A-dependent regulation, and c-MYC is a key downstream effector in the oncogenic pathway mediated by METTL3/YTHDF-coupled epitranscriptomal regulation." (PMID 41167308, 2025). "In esophageal squamous cell carcinoma (ESCC), METTL3 and YTHDF collaborate to downregulate adenomatous polyposis coli (APC) expression, thereby activating the Wnt/β‐catenin signaling pathway and promoting aerobic glycolysis." (PMID 38721006, 2024). "In esophageal squamous cell carcinoma (ESCC), RBM15 interacts with METTL3 in a WTAP-dependent manner to deposit m6A on LncMALAT1." (PMID 36854773, 2023). "The EGR1 mRNA underwent m6A modifications through the action of METTL3, and YTHDF3 enhanced its RNA stability to upregulate the EGR1/Snail signaling pathway and support cancer metastasis in esophageal squamous cell carcinoma." (PMID 37012388, 2023).
esophageal squamous cell carcinoma (continued). "The anti-HIV drug elvitegravir inhibited metastasis by directly targeting METTL3 and enhancing stress-inducible phosphoprotein 1 homology and U-box containing protein 1 (STUB1)-mediated proteasomal degradation in esophageal squamous cell carcinoma (ESCC)." (PMID 37391814, 2023). "However, the immunological role, possible immune mechanism, and clinical significance of METTL3 in esophageal squamous cell carcinoma (ESCC) remain to be confirmed." (PMID 35574315, 2022). "METTL3, WTAP, IGF2BP3, YTHDF1, HNRNPA2B1 and HNRNPC were markedly increased in esophageal squamous cell carcinoma (ESCC) and positively related to the expression of PD-1, whose copy number dynamically affects the enrichment of tumor-infiltrating immune cells." (PMID 36225914, 2022). "Similarly, in esophageal squamous cell carcinoma (ESCC), METTL3 and METTL14 demonstrate distinct functional roles." (PMID 38965238, 2024). "The mechanism of action of METTL3 in esophageal squamous cell carcinoma (ESCC) remains unclear." (PMID 36386128, 2022). "For example, METTL3 is significantly up-regulated in esophageal squamous cell carcinoma, and this leads to a worse prognosis through activating Notch signaling pathway." (PMID 35449086, 2022). "In esophageal squamous cell carcinoma (ESCC), ZC3H13 modulates METTL14/METTL3 nuclear transport and stabilizes CXCL8 mRNA, driving M2 polarization and infiltration, thereby facilitating immune evasion." (PMID 41164187, 2025). "A pan-cancer analysis leveraging The Cancer Genome Atlas (TCGA) data has identified pronounced disparities in the expression patterns, functional roles, and correlations with tumor burden between METTL3 and METTL14, particularly in esophageal squamous cell carcinoma (ESCC)." (PMID 38965238, 2024).
myeloid leukemia (27 papers, 2017 to 2025). A clonal proliferation of myeloid cells and their precursors in the bone marrow, peripheral blood, and spleen. "METTL3 deficiency induces the differentiation and apoptosis of human myeloid leukemia cell lines, partially being ascribed to the increased levels of phosphorylated AKT." (PMID 30405719, 2018). "In human myeloid leukemia (MOLM13) cells with METTL3 depletion, the level of m6A modification of BCL-2 is reduced, correlating with decreased protein expression." (PMID 39686999, 2024). "Small molecule METTL3 inhibitors have already shown promising results in other diseases such as acute kidney injury or myeloid leukaemia." (PMID 36899967, 2023). "STM2457, a new bioavailable inhibitor of METTL3, was developed in 2021 as a new drug to treat myeloid leukemia." (PMID 36609413, 2023). "Subsequently, methyltransferase-like 3 (METTL3), methyltransferase-like 14 (METTL14), Wilm’s tumor 1-associated protein (WTAP), and AlkB homolog 5 (ALKBH5) were reported to be related to myeloid leukemia." (PMID 35720276, 2022). "The increased number of THP-1 (human myeloid leukemia mononuclear) cells adhering to HUVECs by OS or siMETTL3 was relieved in the presence of overexpression of METTL3 or AG1478." (PMID 35001873, 2022). "It has been reported that silencing of METTL3 in human hematopoietic stem/progenitor cells and human myeloid leukemia cells promotes cell differentiation and apoptosis, while overexpression of METTL3 has opposite effects." (PMID 35154467, 2022). "Recently, a role for METTL3 in regulating myeloid differentiation and maintaining myeloid leukemia has been reported." (PMID 29439529, 2018). "The METTL3 inhibitor STM2457 has been developed to target myeloid leukemia." (PMID 40591025, 2025). "A recent study found that STM2457 exhibited therapeutic effects in myeloid leukaemia, indicating that METTL3 targeted therapy may be effective against this disease." (PMID 40520008, 2025). "Moreover, we found from the dataset analysis that METTL3 was enriched in T cell differentiation and methyltransferase complex and highly expressed in myeloid leukemia." (PMID 35761379, 2022). "Meanwhile, METTL3 has been documented to accelerate myeloid leukemia." (PMID 35761379, 2022). "In addition, a recent study published in Nature pointed out that STM2457, a small molecule inhibitor of METTL3, can significantly inhibit the progression of myeloid leukemia." (PMID 35449193, 2022). "In the context of human myeloid leukemia, specifically the MOLM13 cell line, prior studies have emphasized the significance of METTL3 in regulating the expression of BCL2, c-Myc, and PTEN." (PMID 40453361, 2024). "Although each of the major proteins in the m6A methylation complex—that is, RBM15, WTAP, METTL3, and METTL14—show alterations in myeloid leukemias, definitive demonstration of the role of m6A will require mechanistic evidence linking m6A alterations to leukemia phenotypes in these cancers." (PMID 28081722, 2017).
nasopharyngeal carcinoma (27 papers, 2019 to 2025). A carcinoma arising from the nasopharyngeal epithelium. "This discovery highlights METTL3 as a potential therapeutic target in EBV-associated diseases such as nasopharyngeal carcinoma (NPC), Hodgkin’s lymphoma, and GC, indicating the clinical application prospects of UZH1a." (PMID 39295872, 2024). "METTL3 is highly expressed in nasopharyngeal carcinoma tissues and affects the overall survival of patients with nasopharyngeal carcinoma." (PMID 34136491, 2021). "Correlation between METTL3 expression and clinicopathological characteristics in nasopharyngeal carcinomas (number = 55, χ2-test)." (PMID 32596151, 2020). "In nasopharyngeal carcinoma (NPC), METTL3 has been shown to induce high m6A enrichment in TRIM11, a tripartite motif-containing protein family member that positively modulates β-catenin signaling, to promote cisplatin resistance." (PMID 34315512, 2021). "In the context of nasopharyngeal carcinoma (NPC), it was observed that the levels of m6A modification and METTL3 expression were significantly higher in tumor tissues than in neighboring tissues." (PMID 38576024, 2024). "In nasopharyngeal carcinoma, TRIM11 is upregulated by a METTL3-mediated m6A modification that regulates β-catenin signaling to promote cisplatin resistance." (PMID 39199429, 2024). "In nasopharyngeal carcinoma (NPC), the lncRNA ZFAS1, whose RNA stability is enhanced by the m6A methyltransferase METTL3, promotes NPC cell proliferation, migration and tumor growth and regulates autophagy levels by modulating the miR-100-3p/ATG10 axis and through the PI3K/AKT pathway." (PMID 38933333, 2024). "In nasopharyngeal carcinoma (NPC), METTL3-mediated m6A modification was enriched in TRIM11 mRNA and stabilized it depending on IGF2BP2." (PMID 36810281, 2023). "In drug-resistant nasopharyngeal carcinoma cells, the m6A modification of TRIM11 mediated by METTL3 promotes the stability of TRIM11 mRNA through the m6A-IGF2BP2-dependent pathway, which partially increases the expression of the TRIM11 protein." (PMID 34858499, 2021). "Similarly, highly expressed METTL3 in drug-resistant cell lines was also found in nasopharyngeal carcinoma (NPC)." (PMID 34745970, 2021). "In personalized treatment, integrating METTL3 and SLC7A11 expression levels for patient stratification may offer more precise treatment plans for nasopharyngeal carcinoma patients." (PMID 39990661, 2025). "Similarly, METTL3 inhibits the expression of ZNF750 and then promotes apoptosis through the NF750-FGF14 signal axis in nasopharyngeal carcinoma." (PMID 34858499, 2021). "Additionally, METTL3 stabilizes the super-enhancer lncRNA SUCLG2-AS1, facilitating the formation of a long-range chromatin loop between the SOX2 enhancer and promoter, which promotes nasopharyngeal carcinoma metastasis and radiation insensitivity." (PMID 41390674, 2025). "For example, in nasopharyngeal carcinoma (NPC), TRIM11 is upregulated by METTL3-mediated m6A modification, which modulates β-catenin signaling, thus promoting cisplatin resistance." (PMID 36960074, 2023). "METTL3 has also been shown to increase the stability of FAM225A, a lncRNA overexpressed in nasopharyngeal carcinoma (NPC), to promote tumorigenesis." (PMID 32911345, 2020).
diabetes (26 papers, 2020 to 2025). "Conditional ablation of METTL3 in pericytes suppresses diabetes-induced retinal pericyte loss, vascular leakage, and vascular lesions in vivo." (PMID 34987645, 2022). "Moreover, conditional pericyte knockout of Mettl3 can reduce pericyte loss and diabetes-induced retinal vascular complications." (PMID 34987645, 2022). "Later, it was discovered that both the m6A level and METTL3 expression were increased in the livers of patients with type 2 diabetes mellitus (T2DM), and their expression was positively associated with IR by promoting the expression of fatty acid synthase (Fasn)." (PMID 35692393, 2022). "There is growing evidence that METTL3 is strongly associated with diabetes mellitus (DM), including insulin deficiency, hyperglycemia and insulin resistance." (PMID 41194259, 2025). "However, the role of METTL3 in the regulation of diabetes associated diseases is controversial, and the association between METTL3 and DR pathogenesis is still largely unknown." (PMID 32365051, 2020). "In the context of diabetes mellitus (DM), the upregulation of m6A modification mediated by METTL3 suppresses the expression of key genes, including PKC-η, FAT4, and PDGFRA." (PMID 41315216, 2025). "m6A RNA methylation levels and METTL3 expression were significantly up-regulated in pericytes and mouse retinas following diabetic stress, and pericyte-specific Mettl3 knockout inhibited diabetes-induced pericyte dysfunction and vascular complications in vivo." (PMID 41585810, 2025). "METTL3 has been recognized as an essential factor in conditions including diabetes, cancers and cardiovascular disease." (PMID 34185971, 2022). "IB4 and NG2 immunofluorescence staining showed pericyte-specific deletion of Mettl3 significantly decreased diabetes-induced pericyte dysfunction in Mettl3f/f; Pdgfrβ-Cre mice compared with the control group." (PMID 34987645, 2022). "METTL3 silencing in vitro or conditional knockout of METTL3 in vivo protects pericytes against diabetes-induced injury." (PMID 34987645, 2022). "Compared to normal retinas, diabetes led to increased levels of Mettl3 in the retinas both at mRNA and protein levels." (PMID 34987645, 2022). "Under diabetic stress, METTL3 silencing can protect pericytes against diabetes-induced pericyte dysfunction and alleviate BRB breakdown in vitro." (PMID 34987645, 2022). "For instance, methyltransferase-like 3 (Mettl3)-mediated m6A modification was reported to be connected to hepatogenous diabetes in mice fed a high-fat diet (HFD)." (PMID 35692393, 2022). "Evans blue assay showed that pericyte-specific deletion of Mettl3 reduced diabetes-induced retinal vascular leakage." (PMID 34987645, 2022). "Specific depletion of METTL3 in pericytes suppressed diabetes-induced pericyte dysfunction and vascular complication in vivo." (PMID 34987645, 2022). "In human pathophysiology, METTL3 has been recognized as an essential factor, including diabetes, cancers and cardiovascular disease." (PMID 33099572, 2020). "Of note, recent literature has suggested that METTL3-meditated m6A modification might govern pericyte dysfunction during diabetes-triggered retinal vascular complications." (PMID 39407268, 2024). "In addition to vascular diseases such as AS and restenosis, the role of METTL3 in other vascular conditions like hypertension, aneurysms, and vascular complications of diabetes should be investigated." (PMID 39834386, 2024). "Study suggests that METTL3-mediated m6A methylation regulates diabetes-induced pericyte dysfunction, which could be a potential therapeutical target for diabetes-induced retinal vascular complication treatment." (PMID 36896007, 2023). "First, the RNA-Seq results indicated that, in addition to Fto overexpression in diabetes, Mettl3 was slightly downregulated, suggesting that this writer may also contribute to reduced m6A in diabetes." (PMID 37781923, 2023).
diabetes (continued). "Moreover, upregulation of METTL3 was found in lens epithelial cells derived from patients with diabetes with cataracts." (PMID 35692393, 2022). "Thus, silencing of METTL3 can become a promising strategy for the treatment of diabetes-induced retinal vascular complications." (PMID 34987645, 2022). "Recent studies found that methyltransferase-like 3 (METTL3) mediated m6A modifications were closely related with the development of type 2 diabetes mellitus (T2DM), but it was still unclear whether METTL3 regulated DR progression." (PMID 32365051, 2020). "Thus, METTL3/14 might be potential therapeutic targets for the treatment of β-cell failure in diabetes." (PMID 35692393, 2022). "The ability of a sustained over-expression of Mettl3 in β-cells to limit the up-regulation of Oas and protect the non-obese diabetic (NOD) mouse model of T1D28 from developing diabetes supports the translational significance of these findings." (PMID 38409327, 2024). "In patients with type 2 diabetes (T2D), m6A levels were reduced, while the mRNA levels of FTO, METTL3, METTL14, WTAP were significantly elevated and involved in the pathogenesis of diabetes." (PMID 34026872, 2021). "METTL3 significantly modulated HFD-induced metabolic disorders, insulin sensitivity, and hepatogenic diabetes." (PMID 34084770, 2021). "We found 15 differentially-expressed genes among 20 RNA m6A methylation regulators, including EIF3C, FTO, METTL3, RBM15, etc; and 40 differentially-expressed genes among 46 diabetes related factors." (PMID 34084770, 2021). "In addition, both METTL3 mRNA and miR-25-3p were low-expressed in the peripheral venous blood samples of diabetes mellitus (DM) patients compared to normal volunteers, and high-glucose inhibited METTL3 and miR-25-3p expressions in RPE cells." (PMID 32365051, 2020). "Consistently, in vivo gene therapy to prolong Mettl3 overexpression specifically in β-cells delayed diabetes progression in the non-obese diabetic (NOD) mouse model of T1D." (PMID 38409327, 2024). "Due to the critical role of METTL3 in pericytes and ECs, it is not surprising that METTL3 is involved in diabetes-induced retinal vascular complications." (PMID 34987645, 2022). "Similarly, it is reported that METTL3, FTO, METTL14, and WTAP are up-regulated in diabetes patients." (PMID 33748197, 2021). "METTL3-mediated m6A modification of RNAs has a non-negligible role in eye-related diseases, such as proliferative vitreoretinopathy (Wang, Doxtader & Nam, 2016) and diabetes-induced pericyte dysfunction." (PMID 36908822, 2023). "However, Mettl3 expression was significantly downregulated in the liver of diabetes (db/db) mice and obese (ob/ob) mice but not in the liver of alcohol abuse and alcoholism (NIAAA) mice and high saturated fat, cholesterol, and fructose (FFC) diets induced mice compared to the control." (PMID 37335109, 2023).